IGF1R (insulin like growth factor 1 receptor)
Diseases named in the same sentence as IGF1R in open-access papers (continued):
Sharing a sentence is not in itself a finding about the gene and the disease.
cancer (continued). "However, the insulin-like growth factor 1 receptor (IGF1R), an attractive drug target for cancer therapy, is emerging as an important immunomodulator and regulator of key immune cell functions." (PMID 38420122, 2024). "This suggests that colocation with the Golgi apparatus may be a feature of IGF-1R activity in migratory cancer cells." (PMID 39608716, 2024). "However, the relationship between IGF-1R and cancer is complex and can vary depending on the type of cancer." (PMID 38540176, 2024). "Notably, IGF1r has been reported to play a crucial role in regulating cellular metabolism, proliferation, and survival, particularly in the context of cancer." (PMID 38491378, 2024). "To test this hypothesis, we inhibited the activity of IGF1R in EpCAMhigh cancer cells by using 2 different sh-RNA constructs." (PMID 39075581, 2024). "Targeting IGF-1R signaling pathways could represent a potential therapeutic strategy to inhibit lymphatic metastasis and improve patient outcomes in cancer." (PMID 39328205, 2024). "To further test how ITGB1 affects IGF-1R activity, we asked whether ITGB1 influences IGF-1R subcellular location in actively adhering cancer cells." (PMID 39608716, 2024). "Interestingly, we show that ITGAV knockdown in EpCAMhigh cancer cells generates epithelial cSCCs as those obtained after IGF1R inhibition, demonstrating the involvement of ITGAV in EMP." (PMID 39075581, 2024). "It was also revealed that IGF1R might also be significant in the processes of carcinogenesis and chemoresistance in cancer cells." (PMID 39394189, 2024). "The PEc expression may also explain the reduced efficiency of the anti-IGF-1 and anti-IGF-1R mAbs in various cancers." (PMID 39273251, 2024). "Recently, IGF1R has been reported to promote cancer metastasis and drug resistance." (PMID 38292328, 2024). "We conclude that phosphorylation of Tyr1250/1251 may enhance these IGF-1R functions in cancer cells, resulting in a more transformed phenotype." (PMID 39608716, 2024). "Overall, these findings indicate that ITGB1-dependent phosphorylation and trafficking of the IGF-1R enhances its signaling output, which may be critical in promoting an aggressive cancer phenotype." (PMID 39608716, 2024). "Similarly, IGF1R is our other chosen target; it is also strongly expressed in many different cancer types, including ovarian, breast, uterine, stomach, skin, lung, and adrenocortical." (PMID 38666938, 2024). "The insulin-like growth factor 1 receptor (IGF-1R), a member of the receptor tyrosine kinase family, remains unmutated in cancers and exhibits high expression in various tumors, thus establishing itself as one of the most extensively investigated kinase targets." (PMID 38665430, 2024). "Additionally, the insulin-like growth factor 1 receptor (IGF-1R) is recognized as the kinase target in cancer treatment." (PMID 39457613, 2024). "Additionally, IGF-1 and IGF-1R are associated with the development of TC in younger populations, as high expression of IGF-1R enhances the aggressiveness of cancer cells." (PMID 39104813, 2024). "Several strategies have been developed to target IGF1R in cancer." (PMID 38420122, 2024). "Several studies indicated that IGF1R inhibition affected autophagy differently in cancer cells." (PMID 39394189, 2024). "Thus, it is reasonable to conclude that intracellular IGF-1R signaling is a feature of aggressive cancers." (PMID 39608716, 2024). "Notably, significantly reduced total and phosphorylated levels of IGF1R, a gene commonly overexpressed in various cancer types, were found in LS cells." (PMID 38255007, 2024). "The inhibition of IGF-1R has also been revealed to improve therapeutic response to anti-cancer agents in cancers that do not involve EGFR mutations." (PMID 38540176, 2024).
cancer (continued). "Therefore, continued exploration of the intricate connections within the IGF/IGF-1R signaling axis is indispensable for realizing the full therapeutic potential of IGF-1R inhibition in the clinical setting, especially in cancer treatment." (PMID 38540176, 2024). "Furthermore, the IGF-1R accumulates intracellularly at the Golgi in these aggressive cancer cell lines, and drug-induced disruption of the Golgi abrogates IGF-1-mediated activation of SHC." (PMID 39608716, 2024). "IGF-1R in the nucleus may maintain cancer stemness by activating WNT signaling, contributing to therapeutic resistance." (PMID 39273251, 2024). "IGF2 is predominantly secreted by CAFs, whereas IGF1R is predominantly expressed by cancer cells." (PMID 38887298, 2024). "As a result, only fragmentary knowledge of many IGF-1R pathways, not only in cancer, is available." (PMID 39638246, 2024). "Thereby IGF1/IGF1R alteration usually occurs in cancers and metabolic disorders." (PMID 39867883, 2024). "In cancer clinical trials, IGF1R inhibitors have shown manageable toxicity (albeit with limited clinical benefit against many cancers); thus, they may find utility in BPH, particularly if delivery or activity can be restricted to the prostate." (PMID 37971878, 2024). "This may lead to cancer progression (e.g. invasion, metastasis, and/or angiogenesis) via activation of IGF-1R signaling and its downstream mediators β-catenin and slug." (PMID 39638246, 2024). "The remarkable effect of AhR agonists on IGF signaling might also be applicable for combination therapies with IGF-1R inhibitors in other MYB-dependent cancers such as ACC." (PMID 38835346, 2024). "Indeed, a strong accumulation of EpCAMhigh cancer cells was observed in the sh-IGF1R cSCCs, resembling WD-SCCs composed mostly of epithelial cancer cells." (PMID 39075581, 2024). "Overcoming these obstacles may require a comprehensive approach combining IGF-1R inhibition with other selective agents for successful cancer treatment." (PMID 38540176, 2024). "High level of IGF1R gene expression is a typical marker for most cancer types, and the anti-apoptotic and pro-cell survival capabilities of IGF1R may contribute to its role in cancer cells." (PMID 39404930, 2024). "Additional in vitro and in vivo studies using Igf1r-null PDAC cancer cell lines may also be informative." (PMID 38920688, 2024). "Consequently, IGF-1R-targeted therapies for any component of the IGF-1R pathway exhibit anti-cancer effects, such as inhibiting cell proliferation, inducing apoptosis, reducing angiogenesis, and reversing drug resistance." (PMID 38540176, 2024). "In cancer, few studies report the role of the IGF1R pathway in modulating T cell activity." (PMID 38420122, 2024). "Targeting IGF-1R has also been researched as a novel cancer therapy." (PMID 38774165, 2024). "Indeed, EpCAMlow cancer cells with an already acquired cell plasticity, can evolve to the mesenchymal state independently of the IGF1R pathway, generating mesenchymal cSCCs." (PMID 39075581, 2024). "We investigated whether disrupting lysosomal dynamics, alone or in combination with an IR/IGF-1R inhibitor, could sensitize cancer cells to chemotherapy." (PMID 38786030, 2024). "The IGF-1R signaling pathway offers promising targets for cancer therapy." (PMID 38540176, 2024). "Interestingly, radiation exposure induced extracellular vesicle-mediated extrusion of miR-603 from the cancer cell, thereby de-repressing IGF1R." (PMID 38892104, 2024). "In detail, it has been demonstrated that IGF-1R signaling can contribute to malignant transformation and cancer growth and that the upregulation of IGF-1R and IGF-2 as well as the deregulation of their downstream signaling molecules increase the risk of cancer development and invasiveness." (PMID 36902237, 2023). "Consequently, inhibitory reagents targeting IGF-1/IGF-1R have been developed to limit cancer development." (PMID 36831629, 2023).
cancer (continued). "The interaction between GRP78 and IGF1-R molecules suggests that using GRP78 inhibitors to inhibit IGF-1R signaling in cancer cells may be viable." (PMID 37221596, 2023). "High level of glucose provides sufficient energy for rapidly proliferation in cancer cells and promotes cancer development by activating insulin-like growth factor-1 receptor signaling pathways, altering programmed death receptor pathways, and modulating immune detection." (PMID 36860393, 2023). "In contrast to serum IGF-1, IGF-1R activity, especially cytoplasmic and nuclear IGF-1R expression, has been proven to promote radiotherapy resistance and enhance the risk of biological cancer recurrence." (PMID 36831629, 2023). "The interplay between IGF-1R and cell adhesion molecules collectively activates Akt and further signaling pathways to activate the mitotic cascade, thus contributing to the development and aggressiveness of cancers." (PMID 36831629, 2023). "Studies showing prognostic impact of overexpression of IGF-1R in various cancer types." (PMID 37834454, 2023). "A potential reason for the limited anti-cancer impact when IR/IGF1R was targeted may be because multiple signalling pathways are altered in TNBC." (PMID 36920947, 2023). "Genes involved in endocrine resistance pathways primarily fell into 3 functional categories: ERBB2/IGF1R, CCND1, and BCL2, which have been reported to be associated with endocrine resistance and an increased risk of cancer recurrence in breast cancer." (PMID 37328469, 2023). "The Insulin-like growth factor 1 receptor (IGF-1R), one of the most intensely investigated kinase targets, is neither mutated in cancers nor did the clinical trials use a molecular-profile based stratification of patients." (PMID 37858153, 2023). "Cixutumumab is a fully human Mab targeting IGF‐1R, which is involved in cancer development." (PMID 37042307, 2023). "Furthermore, suppression of IGF-1R activity has been proven to enhance radiosensitivity in cancer due to delayed double-strand break repair in cancer cells." (PMID 36831629, 2023). "While this study was conducted in a cancer model with activating mutations of PI3K, it is likely that other mechanisms may contribute to PI3K activity, such as PTEN mutations or IR/IGF1R activation by autocrine IGF2." (PMID 36672737, 2023). "IGF-1R in the Golgi is commonly seen in migratory cancer cells." (PMID 37858153, 2023). "Interestingly, IGF2 was the factor predominantly involved in maintaining cancer cell stemness through a paracrine mechanism involving the IGF1R/Nanog pathway." (PMID 36672737, 2023). "Interestingly, the overactivation of the IGF-2/IR-A loop in cancer cells is a mechanism of adaptive resistance to anti-IGF-1R drugs." (PMID 37834454, 2023). "Dysregulation of IGF1R signaling has been reported in many cancers, especially breast cancer." (PMID 37686528, 2023). "Since the IGF-1R (insulin-like growth factor-1 receptor) route regulates cellular motility, apoptosis, and proliferation, it has been suggested that signalling through this pathway contributes to a variety of cancers." (PMID 36826066, 2023). "While increased IGF1 levels as well as constitutive activation of the IGF1R are important risk factors in cancer, reduced activities of the GHR, IGF1R, insulin receptor and downstream mediators (e.g., AKT, mTOR, FOXO) have been associated with a prolonged lifespan." (PMID 37941907, 2023). "Targeting IGF-1R has been extensively investigated as a strategy in cancer therapy." (PMID 36831629, 2023). "Therefore, both xenograft and syngeneic models of IGF1R attenuation in cancer have shown promise for targeting IGF1R in cancer." (PMID 37237509, 2023). "Autophagy induced by self-DNA and IGF1R inhibitor also resulted in the survival of CD133-positive HT29 stem-like cancer cells, which may play a role in the CRC recurrence." (PMID 36672697, 2023).
cancer (continued). "Insulin-like growth factor 1 (IGF-1) and its IGF-1 receptor (IGF-1R) belong to an important biological system that is involved in the regulation of normal growth, but that has also been recognized as playing a role in cancer." (PMID 36891560, 2023). "There was no statistically significant change in risk for cancer in women with a history of preeclampsia when not considering IGF1R SNP rs20162347 genotype, although the impact on HR+ breast cancer was suggestive." (PMID 36331687, 2023). "Once target gene IGF1R is downregulated, it could trigger the metabolism for the purpose of accelerating cancer cell apoptosis and inhibiting cancer cell proliferation." (PMID 35164166, 2022). "Moreover, when cancer cells are driven by ligands, the cells are driven by ligand-dependent IGF1R activation, which can lead to increased subsequent local IGFBP secretion." (PMID 35992105, 2022). "Finally, the review summarized ongoing studies on IGF/IGF-1R signaling blockade in multiple cancers and highlighted the IGF-1R signaling modifications in stem cells as a potential strategy to improve stem cell-based therapeutics in regenerative medicine." (PMID 36233084, 2022). "Cancer could use insulin to compensatorily activates multiple signal pathways to escape from IGF-1R inhibitors." (PMID 35252207, 2022). "The analysis of the IGF-1R gene expression between diverse cancer types and adjacent normal tissues across The Cancer Genome Atlas (TCGA) cohort revealed high gene expression in COAD (n = 458) compared to the adjacent normal tissues (n = 41) (P < 0.05) from Sangerbox dataset." (PMID 35931997, 2022). "The involvement of IGF-1R overexpression in the development, progression, metastasis, and therapy resistance of several malignancies, such as breast, prostate, pancreatic, and ovarian cancers, is well documented in both preclinical and clinical studies." (PMID 35890370, 2022). "The IGF/IGF-1R signaling has been reported to play an important role in cancer development." (PMID 36233084, 2022). "IGF-1R may drive neoplastic initiation and progression along the colorectal normal mucosa-polyp-cancer sequence." (PMID 35931997, 2022). "IGF1R, one kind of transmembrane tyrosine kinase receptor, has been accepted its role in modulating cell differentiation, proliferation and apoptosis in several cancers." (PMID 33621401, 2022). "Moreover, istiratumab is a bispecific mAb that inhibits both IGF-1R and ErbB3 (IgG1 with two scFvs, phase II) to kill malignant tumors." (PMID 36233084, 2022). "Increased expression of IGF-1R was a compensatory survival mechanism in pediatric cancer cells." (PMID 35399718, 2022). "Furthermore, it has been found in sorafenib-resistant HCC that YAP1 can induce an increase in EMT and high expression of IGF-1R, both of which are highly related to cancer stemness." (PMID 35672802, 2022). "NRP1 has recently been implicated in resistance to cancer therapies including oncogene-targeted therapies and chemotherapy through activation of bypass survival pathways, including receptor-tyrosine kinase pathways such as HER2, EGFR and IGF1R." (PMID 35078508, 2022). "Consistent with the status of IGF1R as a receptor tyrosine kinase and its vigorously established function in promoting cell proliferation and survival, it was identified as a promising target for therapeutic intervention in human cancer patients." (PMID 35784559, 2022). "It is also implicated in anti-cancer drug resistance through several signaling pathways activated by BPA binding to nuclear and membrane receptors such as ERα/β/γ, androgen receptor, and insulin-like growth factor-1 receptor (IGF-1R), among others." (PMID 35628159, 2022). "This alludes to a model whereby activation of IGF1R/AKT axis promotes survival of cancer cells with complex IV dysfunction by driving glycolysis, while concomitant suppression of mTOR is required to decrease energy consumption and thus compensate for disrupted mitochondrial ATP production." (PMID 35302710, 2022).
cancer (continued). "Interestingly, we observed that miR-223 inhibited IGF1R expression and reduced cancer growth and migration." (PMID 36430468, 2022). "Additionally, signaling via insulin-like growth factors (IGF)-1R has been demonstrated to play a key role in malignant transformation, anti-apoptosis, and metastatic behavior in a variety of cancers." (PMID 36499216, 2022). "In males, KEGG pathway analysis revealed significant overrepresentation of genes involved in endocytosis and pathways in cancer, including IGF1R, which was previously shown to respond to diet-induced metabolic stress in animal models and in lymphocytes in the context of childhood obesity." (PMID 35500004, 2022). "Both the insulin-like growth factor 1 receptor (IGF-1R) and epidermal growth factor receptor (EGFR) were implicated in the development, progression, metastasis, and chemotherapy resistance of a variety of cancers." (PMID 36142299, 2022). "Furthermore, IGF1R inhibition has been shown to have different effects (i.e., inhibitory or stimulatory) on autophagy in cancer cells." (PMID 35651701, 2022). "Furthermore, IGF1R overexpression corresponds to poor prognosis in other cancers, such as breast cancer, where it regulates EMT." (PMID 36289686, 2022). "However, low-level IGF-1R expression is found in some invasive cancers, which promotes cancer cell dedifferentiation to a mesenchymal type morphology with loss of cell adhesion." (PMID 35931997, 2022). "Previous studies have shown that cholesterol-lowering drugs could inhibit AKT signaling in cancer cells by downregulating IGF1R expression." (PMID 36149602, 2022). "Moreover, IGF1R deficiency also reduced proliferation, DNA damage, senescence, vascularization, EMT and fibrosis in the lung TME, most of which are considered cancer hallmarks." (PMID 35688943, 2022). "Application of manuka honey (alone or in combination with 5-fluorouracil) on HCT-116 cell line decreased physical parameters of colonospheres and the survival ability of cancer cells, but also induced apoptosis via down-regulation of apoptosis inhibitors, including IGFs and IGF1R." (PMID 36013453, 2022). "Moreover, inhibition of GRK2 enhanced degradation of cancer-relevant insulin-like growth factor-1 receptor (IGF1R) and prevented its interaction with recruited β-arrestin 2, restraining malignant cell growth." (PMID 35430346, 2022). "In addition to healthy tissues, IGF1R is commonly over-expressed, and the signalling pathway constitutively activated in numerous cancers contributing to mesenchymal transition of stroma cells and malignant development." (PMID 36105797, 2022). "BMS-536924, an IGF-1R inhibitor, when added into the DORexo-treated BMSCs, could inhibit the promotion of cancer cell proliferation cocultured with the DORexo BMSCs (P < 0.05)." (PMID 36568212, 2022). "It appears from the data presented above that IGF-1-R signaling targeting could be an excellent therapeutic strategy in cancer, particularly in chemotherapy resistant cases." (PMID 36017326, 2022). "Briefly, CD146- fibroblasts were able to activate IGF1R tyrosine kinase signalling in the cancer cells that drove their oestrogen-independent growth, and was, therefore, hypothesised to be the cause of the irresponsiveness of cancer cells to the treatment." (PMID 34298736, 2021). "Notably, the activation of the PI3K/AKT/mTOR pathway occurs in many types of cancer, and is one of the key downstream transduction signaling pathways of the IGF1R/IRS1 interaction." (PMID 33723215, 2021).